FOXP3 (forkhead box P3)
Diseases named in the same sentence as FOXP3 in open-access papers (continued):
Sharing a sentence is not in itself a finding about the gene and the disease.
tumor (continued). "The Foxp3+ regulatory cells (Tregs), playing a critical role in immune tolerance and deficiency of anti-tumor immunity, were often used as a negative antitumor parameter." (PMID 36081505, 2022). "Next, the levels of FOXP3 and Ki-67 from these tumor tissues were detected by IHC staining." (PMID 36522683, 2022). "By contrast, N2 contains non-infiltrating cells that express CD8, PD1 and FoxP3 (P2) associated to tumor CK+ cells (P7), and is associated with POLE mutated patients." (PMID 35217454, 2022). "Indeed, the reduction of FOXP3+CD4+ Treg cells in tumor tissue after anti-CTLA-4 mAb (Ipilimumab) treatment was strongly associated with clinical benefit." (PMID 35601491, 2022). "Hence, PD-L1 and FOXP3, a marker used to label the regulatory T cells, were evaluated in tumor samples from mice with CT-26 cell-induced CRC." (PMID 36614038, 2022). "We also performed IHC staining for Foxp3 in all tumor samples to label Tregs." (PMID 36158119, 2022). "IMC analysis revealed the recruitment of FoxP3+ T cells and mast cells colocalizing in some tumor regions that contained also reduced HLA-class I expression and CD8+GranzymeB+ cells and were in this manner consistent with the acquisition of resistance to anti-PD-1 ICI treatment." (PMID 35432353, 2022). "The high ratio of Foxp3+ Tregs to CD4+ effector Tcells in subcutaneous tumours may explain why they are refractory to PD-1 blockade.Conversely, the reduced fraction of Tregs in orthotopic tumours may explain theminimal response to CTLA-4 blockade." (PMID 35930804, 2022). "VEGF could promote FOXP3+ Treg cell migration and its immunosuppressive function, but the detailed mechanisms underlying VEGFR blocking therapy and tumour-infiltrating FOXP3+ Treg cells reduction are still unclear." (PMID 36569832, 2022). "Similarly, fewer red fluorescence signals of Gr-1 (Ly6G/Ly6C; the marker of MDSCs) and FoxP3 (forkhead box P3; the marker of Tregs) were observed in the tumor tissues from HDDA-treated mice, indicating the decreased number of MDCSs and Tregs." (PMID 36319625, 2022). "It is believed by some that FOXP3 inhibits tumor metastasis and growth, and induces apoptosis." (PMID 36235242, 2022). "The relationship between tumor cells and FOXP3 has received increasing attention." (PMID 36185217, 2022). "Notably, they established that CD8+T cell exclusion caused by CAFs was dependent on IL-6, as tumours regularly injected with IL-6 mirrored the effects of CAFs and IL-6 blockade caused a significant shift in the TIL population from FoxP3+ to CD8+ T cells." (PMID 35479076, 2022). "The role of FOXP3 in malignant tumor cells is currently controversial." (PMID 36550816, 2022). "Forkhead box P3 (FOXP3)+ regulatory T cells (Tregs) were enriched in the TA-TLS as reported, and some FOXP3+ nuclei (25.9% on average) were co-stained for Ki67, showing the phenotype of tumour-associated proliferating Tregs." (PMID 34779486, 2022). "The translational in vivo tumor model suggested that altering the expression of either CCR4 or FOXP3 in cancer patients could improve the efficacy of chemotherapy or immunotherapy." (PMID 35222362, 2022). "Additionally, the population of intra-tumor CD4+CD25+Foxp3+ T cells was significantly lower in naringenin + CPT treated animals than that in controls." (PMID 35606804, 2022). "FOXP3 regulates the expression of downstream genes by binding with the promoter region or other transcription factors and is involved in the biological functions of tumor cells." (PMID 36185217, 2022). "The correlation between PDLIM2 expression and immune cell marker genes suggests that PDLIM2 can control the infiltration and interaction of immune cells in the tumor microenvironment, and Treg-like immunosuppression can be induced by inducing Foxp3 expression in naïve T cells." (PMID 35121770, 2022). "On the contrary, cancer angiogenesis could conversely exert an effect on tumour-infiltrating FOXP3+ Treg cells." (PMID 36569832, 2022).
tumor (continued). "To get mechanistic insights into the role of Treg-derived CD27 with combinatorial PD-1 signaling blockade on CD8+ T cell mediated antitumor immunity, we analyzed numbers and effector functions of tumor infiltrating CD8+ T cells in MC38-bearing FoxP3.Luci-DTR5 + CD27 − / − mixed chimeric mice." (PMID 34423375, 2022). "Our data also show that patients with high densities of suppressor FoxP3+ or CD163+ cells in their tumor center or the invasive margin, albeit with high numbers of CD8+ cells, had trends for shorter OS compared to those who displayed low FoxP3+ or CD163+ cell frequencies." (PMID 36551693, 2022). "Interestingly, higher percentages of tumor‐infiltrated FOXP3+ Helios− Tregs were seen in advanced‐stage NSCLC with poorer survival." (PMID 35474948, 2022). "Interestingly, we observed a significant reduction in tumor-infiltrating CD4+ FoxP3+ T cells in 4NQO-exposed mice receiving BRB-E-supplemented feed compared to those receiving only the AIN-76 control diet." (PMID 36016924, 2022). "Both samples showed increased CD8+ cell density and decreased FOXP3+ cell density in tumor tissues." (PMID 36479108, 2022). "Substantial numbers of VEGF-C+ CD68+ CD163+ TAMs were distributed in the lesional skin of Merkel cell carcinoma, and expression of CD200 in tumor cells induces immunosuppressive CD163+ CD200R+ M2 TAMs and Foxp3+ Tregs to maintain the immunosuppressive tumor microenvironment." (PMID 35409404, 2022). "IL-33/ST2 signaling suppresses IL-17A production and potentially promotes the conversion of IL-17-producing CD4+ T cell types to IL-17-negative (RORγt−) ST2+ FOXP3+ Treg cells, modifying the inflammatory signals within the tumour microenvironment to promote CRC." (PMID 36569832, 2022). "Meanwhile, both FOXP3+ Tregs and tumor-derived FOXP3 are expressed in TME, due to the complexity between the cross-talk of FOXP3+ Tregs and FOXP3+ tumor cells, and it is necessary to further study the performance of communication mechanisms and their effect on tumor biological behaviors." (PMID 36235242, 2022). "An immunoscore based on combined CD4 and FoxP3 intraepithelial expression may serve as an indicator of advanced tumor progression and should be further investigated for its use as potential prognostic biomarker in OSCC." (PMID 34626165, 2022). "Additional correlation analyses showed that IL7R expression was significantly associated with markers of cells involved in immunosuppression such as CD68, CD163, MRC1, and IL10 (tumor‐associated macrophages), CD4, FOXP3 (regulator T lymphocytes) and CD274 (PD‐L1)." (PMID 36054746, 2022). "At the same time, the expression of CD8 and FoxP3 in tumor tissue was detected." (PMID 35783156, 2022). "Correspondence with IHC-based Treg estimates were also poor, including for FOXP3 expression on the gene and protein levels, although this could be attributed to intra-tumor heterogeneity resulting from analyses of parallel tumor samples." (PMID 35484226, 2022). "Moreover, high levels of tumor-infiltrating TIM-3+ and FoxP3+Helios−TIM-3+ CD8+ Tregs were associated with better DFS." (PMID 35804964, 2022). "Similarly, an abundance of KLRG1+Foxp3+CD4+ T cells appear to accrue in the tumor microenvironment of ovarian and colon cancer, suggesting their role in impaired antitumor immunity." (PMID 35572605, 2022). "Foxp3+ regulatory cells (Tregs), playing a critical role in immune tolerance and deficiency of anti-tumor immunity, were often used as negative antitumor parameters." (PMID 36081505, 2022). "Considering the high proportion of Tr1 cells (considered as CD4+CD49b+Foxp3− T cells) found in the tumor site, we decided to test whether targeting CD49b could prevent tumor growth." (PMID 35860556, 2022). "When a tumor progresses, the ratio of FOXP3 to CD8 expression shifts toward FOXP3." (PMID 35358193, 2022). "In our study, we have identified FOXP3 as a tumor-promoting factor in ESCC." (PMID 36522683, 2022).
tumor (continued). "Furthermore, CD4+ CD25+ Foxp3+ Tregs are currently considered one of the most important immune cell subsets that promote immune escape and tumor growth in the immunosuppressive TME." (PMID 34968167, 2022). "Immunosuppressive cells [i.e., regulatory T cells (Tregs, Foxp3+ T)] are a part of infiltrating CD4+T-cell in the TME, which significantly inhibit the T-cell-mediated anti-tumor effect and may be associated with T-cell dysfunction." (PMID 35720388, 2022). "Tumor-infiltrating FoxP3+ Treg cells are heterogenous in terms of phenotype and function." (PMID 35158783, 2022). "A Cox stepwise regression five-year DSS analysis was performed including age at diagnosis, T stage of tumor, Foxp3-positive TIL level, and whether HPV and/or p16 positive." (PMID 35326661, 2022). "In summary, these studies demonstrated that miR-128-3p could serve as an essential regulator of tumor immunity by modulating the enrichment of CD4+ CD25+ Foxp3+ Tregs by targeting IL16 expression in GC." (PMID 34968167, 2022). "In Treg cells, FOXP3 can inhibit cytotoxic T cells from attacking tumor cells." (PMID 35036444, 2022). "This discrepancy may be explained by the difficulties in defining the identity of suppressive FOXP3+ Treg cells at the tumor site." (PMID 35874729, 2022). "Foxp3+ lymphocytes have been reported to suppress anti-tumor immunity, which worsens survival." (PMID 35915403, 2022). "In contrast, Foxp3+ cells (regulatory T cells, Tregs) are observed to infiltrate into the tumor." (PMID 35392957, 2022). "In addition, CXCR4/FOXP3 double staining in Treg was carried out to confirm the TIL balance in the tumor microenvironment." (PMID 35358193, 2022). "In our third experiment of mice, the gut microbiome environment of ABT+FMT mice approached balance, and the expression of Foxp3 in the brain was upregulated, suggesting that the tumor growth of ABT+FMT mice was relatively slow, which was also consistent with our living imaging results." (PMID 35345443, 2022). "Finally, we evaluated the possible immune-regulatory function of PD-L2 on CD68+ macrophages and CD4+Foxp3+ Treg cells in the tumor microenvironment in NPC." (PMID 36606190, 2022). "Activated tumor-infiltrating Tregs (CD4+Foxp3+ICOS+Ki67-; cluster 13) were also significantly reduced in both combination chemo‐immunotherapy treated groups (5-FU+ICB: 0.25 ± 0.20%; cisplatin+ICB: 0.29 ± 0.31%) compared to PBS controls (2.73 ± 1.01%; p = 0.015; p = 0.014 respectively)." (PMID 35634282, 2022). "Our findings revealed a novel role for FOXP3 in the regulation of CCR4 expression in tumor-infiltrating Tregs and gave a molecular insight as to how immunosuppressive Tregs infiltrate into the TME, allowing us to disrupt the pathway implicated and increase cancer immunity." (PMID 35222362, 2022). "The anti-tumor function of T cells in TME may be suppressed by the FOXP3+ regulatory T cells (Treg) activity or by the PD-1 (programmed cell death 1)/PD-L1 (PD-1 ligand) interactions." (PMID 36359314, 2022). "FOXP3 expression decreased in tumor-bearing mice demonstrating a switch to activate CD4+ T cells." (PMID 35782876, 2022). "The role of CD8+FoxP3+ cells in normal and tumor settings remains to be established." (PMID 35979372, 2022). "Furthermore, PD-L1 expressed on the surface of tumor cells and Foxp3 + T regulatory cell interactions lead to diminished CD8 + effector T cell-mediated antitumor responses and cause exhaustion of effector T cells in the body." (PMID 36591504, 2022). "Correspondingly, when IDO1 was highly activated in MDSCs, the increased infiltration of CD4 + CD25 + FoxP3 + Tregs and the enhancement of immunosuppressive function could be observed in the tumor." (PMID 35681736, 2022). "FOXP3 is expressed in many tumor cell lines and tumor cells in tumor tissues." (PMID 36185217, 2022). "FOXP3-positive regulatory T-cells (Treg) are believed to mediate the suppression of anti-tumor immunity, which may lead to more aggressive disease." (PMID 35267462, 2022).
tumor (continued). "The number of infiltrating Foxp3+ Tregs was found to correlate with the tumor grade." (PMID 36466873, 2022). "However, a high number of Foxp3+ TILs can be indicative of either better or worse prognosis, depending on the primary tumor site and other accompanying factors." (PMID 35915403, 2022). "Interestingly, a significant correlation was observed in tumor tissues between levels of FoxP3+ Tregs and CD4+PD-1+ T cells (r = 0.548, p = 0.008)." (PMID 35455287, 2022). "However, other studies support our results and showed that CD8+FOXP3+ cells have anti‐tumor cytotoxic activity." (PMID 35451108, 2022). "Here, we observed that low levels of immune-inhibitory factors, such as TOX and Foxp3, as well as high numbers of infiltrated lymphocytes in tumor tissues and high baseline levels of inflammatory cytokines may predict a clinical benefit for auto-TIL treatment." (PMID 35727633, 2022). "The effect of FOXP3 on tumor metastasis in GC is still unclear." (PMID 36235242, 2022). "Tregs have a potential role in the progression of OS, and the impetus of the antitumor efficacy of anti-PD-1 antibodies in OS mouse models may be decreased numbers of FOXP3+Tregs and increased tumor-infiltrating lymphocytes in the tumor microenvironment." (PMID 35967366, 2022). "In addition to MDSCs, Tregs cells also represent a target because tumor infiltrating FoxP3+ CD25+ CD4+ Tregs cells are highly proliferative and suppressive." (PMID 36159809, 2022). "We grouped these samples by tumor type and examined FOXP3, CCL17, and CCL22 expression levels." (PMID 35025968, 2022). "As expected, the patients with ICC harbouring high CD8+ TIL and low FoxP3+ TIL counts in the intra-tumour exhibited the most favourable OS whereas those with low CD8+ TIL and high FoxP3+ TIL counts in the intra-tumour exhibited the worst OS (P < 0.001, log-rank test)." (PMID 35597869, 2022). "In addition, MDSCs promote the proliferation and differentiation of Foxp3+ T regulatory cells (Tregs) and tumor-associated macrophages (TAM), which act in favor of tumor progression." (PMID 35160177, 2022). "An immunoscore based on combined CD4 and FoxP3 intraepithelial expression may serve as an indicator of tumor progression and should be further investigated for its use as a potential prognostic biomarker in OSCC." (PMID 34626165, 2022). "However, when administered in vivo to tumor-bearing C57BL/6 mice, they were able to modulate CD4 + CD25 + Foxp3+ T cells thus correcting the tumor-mediated immune-suppressive microenvironment." (PMID 35163063, 2022). "This is consistent with previous studies of SCC tumors in other areas and suggests that the change in the FOXP3/CD8 ratio might affect tumor growth by enabling tumor cells to evade attack by TILs in the tumor microenvironment." (PMID 35358193, 2022). "FOXP3+ Tregs exert immunosuppressive functions in the tumor settings by restricting the development and activation of anti-tumor effector cells and facilitating the tumor immune escape." (PMID 35912096, 2022). "Interestingly, we observed that the effects of BRB-E on Granzyme B production by CD8+ T cells were restricted to the primary tumor site, suggesting a potential link to BRB effects on CD4+ FoxP3+ Tregs in the tumor microenvironment." (PMID 36016924, 2022). "Foxp3 + T and PD-1 + T cells infiltration in tumor cells mediate tumor immune escape and might be a worse prognosis predictor in breast cancer." (PMID 33837508, 2021). "Moreover, high PD‐1 in the tumour associated with low CD3+, CD8+ and FoxP3+ T‐cells, which are also associated with poorer prognosis." (PMID 33338327, 2021). "A novel subpopulation of CD3-CD4+ cells with high TNFα and Foxp3 expression may modulate the tumor microenvironment and play a proinflammatory role." (PMID 33869005, 2021). "Similarly, CAFs derived from other tumor types also promote the expression and recruitment of FOXP3+CD4+ T cells into the tumor milieu." (PMID 34203869, 2021).
tumor (continued). "Importantly, A. muciniphila was associated with enhanced infiltration of immune cells in tumor sites as CCR9+CXCR3+CD4+ T cells were migrated to the site of tumor, and CD4+ T cells to CD4+FoxP3+ T cells (Tregs) ratio was elevated." (PMID 33369247, 2021). "Indeed, positive correlations between COX2 and Foxp3 expression have been found in multiple tumour tissues." (PMID 34529833, 2021). "Tumor tissues produce large amounts of TGF-β, which plays a pivotal role in promoting the generation and stability of Foxp3+ Tregs in the local tumor microenvironment; this is a critical observation because Tregs localized in the tumor tissues can interfere with the antitumor immune response." (PMID 34248973, 2021). "VEGFR-2+ Tregs in tumor tissues is also associated with clinical outcome since intratumoral FoxP3+ VEGFR-2+ Tregs, unlike intratumoral FoxP3+ VEGFR2- Tregs are significantly correlated with poor overall survival and disease-free survival." (PMID 33854498, 2021). "We could not detect the significant difference between CD70-high and -low tumor in the levels of CD8-positive TIL or FOXP3-positive TIL; however, the number of FOXP3-positive iTIL in CD70-high TSCC was marginally larger than CD70-low TSCC." (PMID 35145909, 2021). "IDO inhibits natural and therapy‐induced antitumour immunity as it catabolises the amino acid tryptophan to generate kynurenine and other immunosuppressive catabolites which activate Foxp3 regulatory T cells and attenuate effector T‐cell responses to inhibit immune‐mediated killing of tumour cells." (PMID 34053179, 2021). "We confirmed that DT depleted Foxp3+ Tregs in tumor-bearing lungs." (PMID 34494649, 2021). "After prognostic analysis with PD-L1/B7-H4 combined with FOXP3/CD163, it was found that the double high group (high PD-L1 high CD163, high PD-L1 high FOXP3 and high B7-H4 high FOXP3) shortened overall survival time, confirming that the inhibitory tumor microenvironment led to poor prognosis." (PMID 34307135, 2021). "TGF-β is a crucial mediator for FOXP3 in tumor infiltrating Tregs." (PMID 34806028, 2021). "During a strong Th1 response, Tregs have been demonstrated to be able to differentiate into a subgroup of Tregs that express both forkhead box P3 (FoxP3) and T-box transcription factor TBX21 (T-bet), which are optimized to suppress the activity of Th1 cells, and are associated with tumor growth." (PMID 34439203, 2021). "Therefore, CTLA-4 inhibitors induce anti-tumor immunity by blocking FOXP3+ Treg cells, resulting in enhanced inhibition of tumor cells." (PMID 34277408, 2021). "Interestingly, many of the top 10 most frequent clones in the IgG and CTX plus IgG groups were Foxp3+ Tregs, indicating that an important role of anti-GITR therapy is eliminating the tumor- and CTX-associated expansion of Tregs." (PMID 34676831, 2021). "Furthermore, the proportion of FOXP3+ regulatory T cells (Tregs) from 4T1 tumor-bearing mice injected with PTX plus ZnPP was lower than that from 4T1 tumor-bearing mice treated with PTX alone." (PMID 33809707, 2021). "In humans, other immune cells, including activated CD4 T-cells, express FoxP3 and some reports even suggest that FoxP3 could be expressed by tumour cells as well." (PMID 35052732, 2021). "Notably, evaluation of tumour compartments showed little consistency with DE results, with the expression of PD-L1 (HR=0.53, p=0.023), FOXP3 (HR=0.5, p=0.026), GITR (HR=0.51, p=0.036), SMA (HR=0.59, p=0.043) implicated in improved outcome." (PMID 35083152, 2021). "On the other hand, immune-suppressive cells, such as FOXP3+ regulatory T-cells (Tregs), also present in the tumor bed, are often associated with a negative prognostic impact." (PMID 32852603, 2021). "Interestingly, in the TIL analysis, the number of tumor-infiltrating Treg (CD25+FoxP3+) cells in the combination group was significantly higher than in the B. longum 420 alone and PBS groups." (PMID 34589578, 2021).